TRAM1 (translocation associated membrane protein 1)
Description:
Involved in the translocation of nascent protein chains into or through the endoplasmic reticulum (ER) membrane by facilitating the proper chain positioning at the SEC61 channel. Regulates the exposure of nascent secretory protein chain to the cytosol during translocation into the ER. May affect the phospholipid bilayer in the vicinity of the lateral gate of the SEC61 channel, thereby facilitating ER protein transport. Intimately associates with transmembrane (TM) domain of nascent membrane proteins during the entire integration process into the ER membrane. Associates with the second TM domain of G protein-coupled receptor opsin/OPSD nascent chain in the ER membrane, which may facilitate its integration into the membrane. Under conditions of ER stress, participates in the disposal of misfolded ER membrane proteins during the unfolded protein response (UPR), an integrated stress response (ISR) pathway, by selectively retrotranslocating misfolded ER-membrane proteins from the ER into the cytosol where they are ubiquitinated and degraded by the proteasome. (Microbial infection) In case of cytomegalovirus infection, participates in US2- and US11-mediated ER-to-cytosol retrotranslocation and subsequent degradation of major histocompatibility complex (MHC) class I heavy chains, thereby decreasing the immune detection by cytotoxic T-cells.
Synonyms: TRAM; TRAMP; PNAS8
Tractability: Antibody: UniProt predicts a signal peptide or a membrane-spanning region. PROTAC: ubiquitination databases record sites on it; its protein half-life has been measured.
Gene: Protein-coding gene on chromosome 8 (70,573,218 to 70,608,449, reverse strand). Ensembl gene ENSG00000067167.
Subcellular location: Endoplasmic reticulum membrane
Pathways (Reactome):
Metabolism of proteins: SRP-dependent cotranslational protein targeting to membrane
Gene Ontology:
Molecular function: protein binding; signaling receptor activity
Biological process: cotranslational protein targeting to membrane; protein insertion into ER membrane; response to unfolded protein; SRP-dependent cotranslational protein targeting to membrane, translocation
Cellular component: endoplasmic reticulum; endoplasmic reticulum membrane; membrane
Genetic constraint (gnomAD): Loss-of-function variants: 15 observed, 43.59 expected, observed/expected ratio (o/e) 0.34, 90% interval 0.23 to 0.53. The upper end of that interval is the gene's LOEUF score, 0.53, which puts it in group 2 of 6, group 1 being the genes least tolerant of losing a copy. Missense variants: 313 observed, 400.21 expected, observed/expected ratio (o/e) 0.78, 90% interval 0.71 to 0.86. Synonymous variants: 170 observed, 140.63 expected, observed/expected ratio (o/e) 1.21, 90% interval 1.07 to 1.37.
Homologues: Orthologues: chimpanzee TRAM1 (99% identical), macaque TRAM1 (99% identical), dog TRAM1 (95% identical), pig TRAM1 (95% identical), mouse Tram1 (93% identical), rabbit TRAM1 (92% identical), guinea pig TRAM1 (87% identical), tropical clawed frog tram1 (81% identical), rat Tram1 (77% identical), zebrafish tram1 (72% identical), Drosophila melanogaster TRAM (41% identical), Caenorhabditis elegans tram-1 (37% identical). Paralogues in human: TRAM1L1 (71% identical), TRAM2 (52% identical).
Diseases named in the same sentence as TRAM1 in open-access papers:
TRAM1 is named in the same sentence as 12 diseases in open-access papers, as found by Europe PMC text mining. Sharing a sentence is not in itself a finding about the gene and the disease. The quoted sentences say what the papers report.
breast cancer (2 papers, 2010 to 2025). A primary or metastatic malignant neoplasm involving the breast. "Initially, overexpression of AIB1, RAC3, and TRAM1 (known as ACTR) was found to promote proliferation in breast cancer (BC) and to confer anti-E2 resistance." (PMID 41154392, 2025). "Recent data from breast cancer cell lines shows that miR-17-5p of the miR17-92 cluster down regulates the proto-oncogenic transcriptional activator AIB1 (amplified in breast cancer 1), also known as SRC-3, TRAM1, NCOA3 and RAC3." (PMID 21532838, 2010).
bladder cancer (1 paper, 2021). "For TRAM1 transcripts, lg10(fc) values are consistent between pooled urine RNA samples of C and HR group and bladder cancer cell lines." (PMID 34764360, 2021). "Based on the qPCR data for TRAM1 circRNAs in bladder cancer cell lines, the expression level of circTRAM1-56 with a high cDNA input of 50 ng per sample is very low." (PMID 34764360, 2021). "Linear and potentially circular TRAM1-specific transcripts were identified in a transcriptome analysis of urine RNA of bladder cancer (BCa) patients versus healthy donors." (PMID 34764360, 2021). "The experimental evidence of TRAM1 transcripts included PCR-based detection in the bladder cancer cell lines ECV-304 and RT-4 and analysis of differential gene expression." (PMID 34764360, 2021). "As a potential tumor marker for BCa, TRAM1 transcripts detected with the convergent primer pair in 10 ng cDNA per sample indicated a high expression level in both bladder cancer cell lines and therefore represent a promising marker candidate for detection in urine." (PMID 34764360, 2021).
COVID-19 (1 paper, 2025). A disease caused by infection with severe acute respiratory syndrome coronavirus 2. "GSEA of the gene sets that characterize tissue-resident alveolar macrophages in severe COVID-19, namely AMØ1 (EGAS00001005634), TRAM1+ (GSE155249), and FABP4+ (GSE145926) on the ranked comparison of the transcriptomes of CHIR-AMØ vs. DMSO-AMØ." (PMID 40365863, 2025).
HCMV infection (1 paper, 2015). "TLR2 biphasic expression was not a loading artifact since probing the same blot for TRAM1, a protein that remains constant during HCMV infection, indicated fairly consistent loading between the lanes." (PMID 25955717, 2015).
hyperopia (1 paper, 2022). A refractive error in which rays of light entering the eye parallel to the optic axis are brought to a focus behind the retina, as a result of the eyeball being too short from front to back. "Also, a GNAS gene was associated with HM, TRAM1, CTNNB1, TENM3 and RUNX with myopia and/or refractive error, and EIF4B with low myopia/hyperopia in Europeans." (PMID 36685896, 2022).
lung disease (1 paper, 2022). "The neighboring genes showing association of expression with DNAm at the identified CpGs included TRAM1, which has been shown to be correlated with FEV1, and DHRS3 whose expression is associated with smoke exposure, a strong risk factor for lung disease." (PMID 35906571, 2022).
myopia (1 paper, 2022). "Several targets of these miRNAs, e.g. GNAS, TRAM1, CTNNB1, EIF4B, TENM3 and RUNX were previously associated with myopia/HM/refractive error in Europeans in genome-wide association studies." (PMID 36685896, 2022).
tumor (3 papers, 2016 to 2021). "In summary, transcripts of the TRAM1 gene locus represented the most promising candidates for potent tumor markers with decreased gene expression in HR patients." (PMID 34764360, 2021). "The high consistency of calculated lg10(fold change) values of both differential gene expression analysis and the robust expression level in cell lines suggest linear TRAM1 RNA species as potential candidates for tumor markers with reduced expression in higher cancer stages." (PMID 34764360, 2021). "Therefore, TRAM1 RNAs could function as potential tumor markers for a non-invasive detection of BCa in urine of patients." (PMID 34764360, 2021).
cancer (2 papers, 2021 to 2022). A tumor composed of atypical neoplastic, often pleomorphic cells that invade other tissues. "Taken together, linear and circular TRAM1 transcripts showed decreased differential gene expression in HR BCa patients and in the higher cancer stage cell culture model." (PMID 34764360, 2021). "Taken together, linear and circular TRAM1 RNA species exhibited decreased differential gene expression in the higher cancer stage of patients and the G3 stage cell model." (PMID 34764360, 2021). "Hence, the low expression levels of TRAM1 circRNAs in cell lines are compatible with other studies on BCa and different cancer types." (PMID 34764360, 2021). "Additionally, functional studies in BCa cell lines including suppression or overexpression approaches could provide deeper insights into roles and involved mechanisms of linear and circular TRAM1 transcripts in cancer development." (PMID 34764360, 2021). "On the biological side, TRAM1-specific circRNAs showed low expression levels and minor differences in BCa cell lines while linear TRAM1 transcripts displayed down-regulated expression in the higher cancer stage model ECV-304 versus more differentiated RT-4 cells." (PMID 34764360, 2021). "The linear TRAM1 transcripts showed decreased expression in urine of HR BCa patients and in ECV-304 cells (G3 cancer stage)." (PMID 34764360, 2021).
infection (1 paper, 2023). The state of being infected such as from the introduction of a foreign agent such as serum, vaccine, antigenic substance or organism. "As the TRAM1 KO Calu-3 cells stopped dividing after infection, probably due to virus-induced cellular senescence, we validated REEP5 KO Calu-3 cells with immunoblot." (PMID 37768083, 2023). "Importantly, we confirmed the endogenous binding between viral NSP3 and REEP5/TRAM1 complex in Calu-3 cells after infection with SARS-CoV-2." (PMID 37768083, 2023).
TRAM1 also shares sentences with these, for which no sentence is quoted: cardiac hypertrophy (1 paper); Neurological Disorder (1).